TWIST1 (twist family bHLH transcription factor 1)
Description:
Acts as a transcriptional regulator. Inhibits myogenesis by sequestrating E proteins, inhibiting trans-activation by MEF2, and inhibiting DNA-binding by MYOD1 through physical interaction. This interaction probably involves the basic domains of both proteins. Also represses expression of pro-inflammatory cytokines such as TNFA and IL1B. Regulates cranial suture patterning and fusion. Activates transcription as a heterodimer with E proteins. Regulates gene expression differentially, depending on dimer composition. Homodimers induce expression of FGFR2 and POSTN while heterodimers repress FGFR2 and POSTN expression and induce THBS1 expression. Heterodimerization is also required for osteoblast differentiation. Represses the activity of the circadian transcriptional activator: NPAS2-BMAL1 heterodimer (By similarity).
Synonyms: bHLHa38; TWIST; SCS; H-twist; BPES2; CRS1; ACS3; BPES3; CRS; CSO; SWCOS
Tractability: PROTAC: ubiquitination databases record sites on it.
Gene: Protein-coding gene on chromosome 7 (19,020,991 to 19,117,636, reverse strand). Ensembl gene ENSG00000122691.
Subcellular location: Nucleus
Pathways (Reactome):
Gene expression (Transcription): Regulation of RUNX2 expression and activity; Transcriptional regulation by RUNX2
Cell-Cell communication: Negative Regulation of CDH1 Gene Transcription
Disease: Nuclear events stimulated by ALK signaling in cancer
Immune System: Interleukin-4 and Interleukin-13 signaling
Gene Ontology:
Molecular function: bHLH transcription factor binding; cis-regulatory region sequence-specific DNA binding; DNA-binding transcription activator activity, RNA polymerase II-specific; DNA-binding transcription factor activity, RNA polymerase II-specific; DNA-binding transcription factor binding; DNA-binding transcription repressor activity; E-box binding; protein binding; histone deacetylase binding; RNA polymerase II transcription regulatory region sequence-specific DNA binding; transcription coregulator binding; DNA-binding transcription factor activity; identical protein binding; protein dimerization activity; protein domain specific binding; protein homodimerization activity
Biological process: aortic valve morphogenesis; cell proliferation involved in heart valve development; cellular response to hypoxia; embryonic camera-type eye formation; embryonic cranial skeleton morphogenesis; eyelid development in camera-type eye; negative regulation of cellular senescence; negative regulation of DNA-templated transcription; negative regulation of double-strand break repair; negative regulation of miRNA transcription; negative regulation of osteoblast differentiation; negative regulation of phosphatidylinositol 3-kinase/protein kinase B signal transduction; negative regulation of transcription by RNA polymerase II; positive regulation of cell migration; positive regulation of DNA-templated transcription initiation; positive regulation of epithelial to mesenchymal transition; positive regulation of fatty acid beta-oxidation; positive regulation of gene expression; positive regulation of interleukin-6 production; positive regulation of monocyte chemotactic protein-1 production; positive regulation of transcription by RNA polymerase II; positive regulation of tumor necrosis factor production; regulation of bone mineralization; cranial suture morphogenesis; and 14 more
Cellular component: nucleus; chromatin; nucleoplasm
Genetic constraint (gnomAD): Loss-of-function variants: 7 observed, 8.99 expected, observed/expected ratio (o/e) 0.78, 90% interval 0.44 to 1.45. That is too few expected variants to judge how well the gene tolerates losing a copy. Missense variants: 209 observed, 200.37 expected, observed/expected ratio (o/e) 1.04, 90% interval 0.93 to 1.17. Synonymous variants: 139 observed, 92.2 expected, observed/expected ratio (o/e) 1.51, 90% interval 1.31 to 1.74.
Gene-disease validity (ClinGen):
ClinGen rates the evidence that TWIST1 causes each of these diseases.
Saethre-Chotzen syndrome (autosomal dominant): Definitive. Saethre-Chotzen syndrome (SCS) is an inherited craniosynostosis syndrome characterized by unilateral or bilateral coronal synostosis, facial asymmetry, ptosis, strabismus and small ears with prominent crus, among other less common manifestations.
TWIST1-related craniosynostosis (autosomal dominant): Moderate. Any craniosynostosis in which the cause of the disease is a mutation in the TWIST1 gene.
Sweeney-Cox syndrome (autosomal dominant): Limited.
Homologues: Orthologues: dog TWIST1 (99% identical), pig TWIST1 (98% identical), mouse Twist1 (97% identical), rat Twist1 (97% identical), chimpanzee TWIST1 (80% identical), tropical clawed frog twist2 (53% identical), Drosophila melanogaster twi (46% identical), Caenorhabditis elegans hlh-8 (28% identical), Drosophila melanogaster CG33557 (20% identical), Drosophila melanogaster Fer3 (18% identical), Drosophila melanogaster Hand (18% identical), Drosophila melanogaster HLH54F (16% identical), and 1 more. Paralogues in human: TWIST2 (64% identical), PTF1A (30% identical), HAND1 (24% identical), SCX (24% identical), TCF15 (24% identical), HAND2 (23% identical), MSC (23% identical), TCF21 (21% identical), FERD3L (21% identical), FIGLA (20% identical), BHLHA9 (18% identical), TCF24 (17% identical), and 1 more.
Diseases named in the same sentence as TWIST1 in open-access papers:
TWIST1 is named in the same sentence as 342 diseases in open-access papers, as found by Europe PMC text mining. Sharing a sentence is not in itself a finding about the gene and the disease. The quoted sentences say what the papers report.
breast carcinoma (446 papers, 2006 to 2026). "Now, this study further suggests that TWIST1 upregulates PD-L1 in breast cancer cells to cause CD8+ T-cell exhaustion." (PMID 38893094, 2024). "High PD-L1 expression is also positively associated with TWIST1 expression in metastatic breast cancers and TNBC cell lines." (PMID 38893094, 2024). "Knockdown of Twist1 reversed the migration and invasion capacities of breast cancer cells and the occurrence of lung metastasis in mice caused by overexpression of USP13." (PMID 36732432, 2023). "TWIST1 has also been shown to promote breast carcinoma invasion and metastasis, and high expression of TWIST1 has been found to be associated with poor prognosis in breast carcinoma." (PMID 37468850, 2023). "Previously, the upregulation of MAPKs was associated with Twist1 overexpression in breast cancer and melanoma." (PMID 36900319, 2023). "We next investigated the causal role of up-regulated Twist1 in FBXO3-induced breast cancer cell migration and tumor metastasis." (PMID 38134227, 2023). "In the control experiments, EGF treatments induced K63-linked ubiquitination of TWIST1 in the BT549 breast cancer cell line." (PMID 36115849, 2022). "Higher expression of SPOP positively correlated with longer survival in TNBC or high-grade breast cancer patients, whereas patients with increased levels of TWIST1 were associated with poor prognosis." (PMID 36115849, 2022). "Reduced SPOP expression, along with elevated TWIST1 levels, is associated with poor prognosis in advanced breast cancer patients, particularly those with metastatic triple-negative breast cancer (TNBC)." (PMID 36115849, 2022). "BHLHE41 expression suppresses apoptosis induced by TNFα in breast cancer cells, TWIST1 expression and migration in human endometrial cancer cells, is also associated with better prognosis of patients with breast cancer with HIF1 protein suppression." (PMID 34768959, 2021). "IL-6 expression in gastric or breast cancer cells strongly enhanced tumor infiltration of TWIST1-expressing cancer-associated fibroblasts." (PMID 32565805, 2020). "Mechanistically, Twist-related protein 1 (TWIST1) was negatively associated with TFPI2 in breast cancer patients, whose expression was decreased by TFPI2 over-expression or increased by TFPI2 knockdown." (PMID 32248791, 2020). "The underlying mechanism involved in regulation of breast cancer progression via TFPI2-mediated TWIST1 was then determined." (PMID 32248791, 2020). "An in vivo study demonstrated that the administration of sunitinib to breast cancer model increases VM channel development and upregulates VM-associated proteins such as Twist1." (PMID 31952335, 2020). "Previous studies have shown that increased Twist1 expression is associated with breast cancer invasion and metastasis." (PMID 30973923, 2019). "In summary, these data indicate that increased CCL2/CCR2 signaling in SUM225 breast cancer cells promotes cell proliferation, and invasion associated with increased TWIST1 and decreased E-cadherin." (PMID 31208996, 2019). "In the current study, lncATB and its downstream gene Twist1 have been applied to the association with the clinicopathological characteristics and survival of breast cancer patients." (PMID 30518916, 2018).
breast carcinoma (continued). "Similar to our findings, a positive association between EMT transcriptional regulators, Twist1 and Snail, as well as PDGFRα expression was shown to be necessary for invadopodia development in breast cancer cells." (PMID 27845909, 2016). "An increased Twist1 expression is associated with decreased ER expression, down-regulation of aromatase enzyme and development of letrozole resistance in breast cancer cells." (PMID 26797644, 2016). "Twist1 is correlated with tumor progression, because it was found to be upregulated in breast cancer and its expression has been associated with poor survival." (PMID 27105506, 2016). "The overexpression of Twist1 was associated with tumor invasion and metastasis, and inhibition of Twist1 with siRNAs suppressed mammary carcinoma cell metastasis." (PMID 26360779, 2015). "More recently, TWIST1 protein has been implicated in various carcinomas, including breast cancer, where it plays a role in metastasis through activation of a biologically latent developmental process called epithelial to mesenchymal transition (EMT)." (PMID 22967435, 2012). "Although our study is a correlative study and cannot reveal causality, it is intriguing and points to a novel role of TWIST1 in breast cancer." (PMID 22967435, 2012). "To explore the underlying biology of TWIST1-associated disease progression in breast cancer, we determined TWIST1 co-expressed genes previously measured on Affymetrix U133A gene-chips." (PMID 22967435, 2012). "AKT and TWIST1 have also been implicated to possess a functional role in de novo angiogenesis in mammary carcinoma." (PMID 23185544, 2012). "Through activation of EMT, TWIST1 promotes the formation and maintenance of breast cancer stem cells and TWIST1 over-expression is implicated in mesenchymal stem cell activity." (PMID 20646316, 2010). "The first study evaluated the presence of TWIST1 gene alterations in cats with mammary cancer since a germline mutation in this gene may predispose to breast cancer in humans." (PMID 38787171, 2024). "Important results on the in vivo cooperation between a breast cancer-associated EMT-TF (Twist1) and the Ras oncoprotein have been obtained in a mouse model, in which the mammary gland-specific expression of the Cre recombinase is driven by the WAP (Whey Acidic Protein) promoter." (PMID 37176013, 2023). "Similarly, aberrant expression of TG2 in breast cancer (BC) was associated with loss of E-cadherin and upregulation of the transcriptional repressors, Snail1, Zeb1, Zeb2 and Twist1." (PMID 35681474, 2022). "Association between Twist1 expression and other molecules in breast cancer patients." (PMID 34249678, 2021). "Weinberg and colleagues found that the EMT-associated transcription factors (Snail1 and Twist1), when expressed in murine mammary carcinoma lines, promote the formation of filopodia-like protrusions (FLPs) which contain integrin β1, enabling interaction with the ECM." (PMID 32391382, 2020). "Similarly, it has been shown that Twist1 (a master regulator of EMT) is associated with multi-drug resistance in breast cancer, however, the mechanism by which Twist1 leads to resistance was not explored." (PMID 32391382, 2020). "Further, AHR hyper-activation with the endogenous ligand FICZ induced migration and invasion-associated (Snai1, Twist1, Twist2, Tgfb1, Vim) and stem cell-associated (Notch1, Notch2, Bmi1, Nanog, Sox2, Dppa3) genes in triple negative ALDHhigh breast cancer CSCs." (PMID 33396563, 2020). "TWIST1 expression was increased in breast cancer cells and decreased in tumor associated stroma in patients with > T1 tumors, while SLUG expression was increased in cancer cells of tumors with low and intermediate grade and in tumors with decreased proliferation (low Ki67)." (PMID 26194471, 2015).
breast carcinoma (continued). "Since Snail has been known to enhance TWIST1 protein stability in mouse breast epithelial NMuMG cells, further study to explore the crosslink between Snail and TWIST1 expression is warranted to determine the underlying mechanism of TGF-β1-induced breast cancer cell EMT and aggressiveness." (PMID 26520789, 2015). "In addition to the prostate cancer cell lines, we also evaluated MCF-7 breast cancer cells, since it has been shown that TWIST1/N-cadherin signaling is deficient in MCF-7 cancer cells." (PMID 26359363, 2015). "Whereas TWIST1 has been convincingly implicated in the metastatic dissemination of breast cancer cells, these data underscore the importance of EMT-inducing transcription factors in driving mammary carcinogenesis, with a dual role in cell transformation and dedifferentiation." (PMID 22654675, 2012). "As a direct target of Twist1 tightly associated with survival in human breast cancer patient tissue samples, PDGFRα is an especially appealing target for therapeutic intervention in breast cancer metastasis." (PMID 21725138, 2011). "Furthermore, in a Stage II breast cancer tissue array from the National Cancer Institute coexpression of Twist1 and PDGFRα was significantly associated with patient survival, indicating the importance of this pathway in human breast tumor progression." (PMID 21725138, 2011). "Recently, Sahrin and colleagues demonstrated an increased risk of breast cancer in women with Saethre-Chotzen syndrome, suggesting that germline mutations in TWIST1 may also predispose to breast cancer." (PMID 21037858, 2010). "In addition to its essential role in modulating the behavior of mesenchymal cell populations critical for development, Twist1 is also an oncogene and is associated with a number of aggressive neoplasias including gastric, liver and most notably breast cancers." (PMID 18855684, 2008). "Therefore, the regulatory mechanism of TFPI2 in breast cancer progression might be associated with TWIST1 expression." (PMID 32248791, 2020). "A study has shown that Twist1 regulates the self‐renewal and metastasis of cancer stem cells in breast cancer and renders cancer cells insensitive to chemotherapy." (PMID 40344465, 2025). "Twist1 has been shown to be regulated by the immune checkpoint PD‐L1 expression in breast cancer cells." (PMID 40344465, 2025). "For example, hypermethylation of the promoter DNA of TWIST1, an EMT transcription factor-encoding gene, is inversely correlated with its expression in different colon and breast cancer cell lines." (PMID 40764968, 2025). "Twist1 expression is abnormally high in many tumours, such as breast cancer, prostate cancer, and hepatocellular carcinoma." (PMID 40344465, 2025). "These all indicate that the suppression of FOXA1 expression by Twist1 plays a substantial role in the Twist1-driven migration, invasion, and metastasis of breast cancer cells." (PMID 40003882, 2025). "TWIST1 enhances E-cadherin promoter hypermethylation and hypoacetylation, driving metastasis while knockdown of TWIST1 inhibits metastasis in breast cancer." (PMID 39858015, 2025). "BC scores and rankings were generated for the Twist1-driver mouse model of epithelial cell dissemination in breast cancer." (PMID 38935814, 2024). "We have shown that TWIST1 interacts with TIP60-Com in a BRD8-dependent manner to activate mesenchymal gene expression in ER- breast cancer or TNBC cells." (PMID 38893094, 2024). "In particular, the expression of TWIST1 in MCF7 breast cancer cells induced Vim and Snai2 expression but repressed CDH1 and ESR1 expression." (PMID 38893094, 2024). "A similar inverse relationship was observed in human breast cancer tissues, where a gradual decline in miRNA-720 correlated with increased TWIST1 protein levels." (PMID 39335152, 2024). "Existing data strongly suggest TWIST1 as a molecular target of metastatic breast cancer as it promotes EMT, cell invasion, metastasis, and drug resistance." (PMID 38893094, 2024).